COPS5 (COP9 signalosome subunit 5)
Description:
Probable protease subunit of the COP9 signalosome complex (CSN), a complex involved in various cellular and developmental processes. The CSN complex is an essential regulator of the ubiquitin (Ubl) conjugation pathway by mediating the deneddylation of the cullin subunits of the SCF-type E3 ligase complexes, leading to decrease the Ubl ligase activity of SCF-type complexes such as SCF, CSA or DDB2. In the complex, it probably acts as the catalytic center that mediates the cleavage of Nedd8 from cullins. It however has no metalloprotease activity by itself and requires the other subunits of the CSN complex. Interacts directly with a large number of proteins that are regulated by the CSN complex, confirming a key role in the complex. Promotes the proteasomal degradation of BRSK2.
Synonyms: SGN5; CSN5; JAB1; MOV-34
Tractability: Small molecule: a structure with a bound ligand is known; a high-quality ligand is known. PROTAC: ubiquitination databases record sites on it; its protein half-life has been measured; a small molecule that binds it is known.
Target class: Enzyme; Hydrolase
Gene: Protein-coding gene on chromosome 8 (67,043,079 to 67,083,783, reverse strand). Ensembl gene ENSG00000121022.
Subcellular location: Cytoplasm, cytosol; Nucleus; Cytoplasm, perinuclear region; Cytoplasmic vesicle, secretory vesicle, synaptic vesicle
Subcellular location (Human Protein Atlas): Nucleoplasm
Pathways (Reactome):
DNA Repair: DNA Damage Recognition in GG-NER; Formation of TC-NER Pre-Incision Complex
Immune System: GSK3B-mediated proteasomal degradation of PD-L1(CD274)
Metabolism of proteins: Neddylation
Vesicle-mediated transport: Cargo recognition for clathrin-mediated endocytosis
Gene Ontology:
Molecular function: metal-dependent deubiquitinase activity; metallopeptidase activity; protein binding; deNEDDylase activity; deubiquitinase activity; transcription coactivator activity; translation initiation factor activity; enzyme binding; macrophage migration inhibitory factor binding; peptidase activity
Biological process: exosomal secretion; negative regulation of apoptotic process; positive regulation of transcription by RNA polymerase II; protein deneddylation; regulation of IRE1-mediated unfolded protein response; regulation of JNK cascade; post-translational protein modification; protein neddylation; regulation of protein neddylation; translation; translational initiation
Cellular component: chromatin; COP9 signalosome; cytoplasm; cytosol; nucleoplasm; nucleus; perinuclear region of cytoplasm; synaptic vesicle; eukaryotic translation initiation factor 3 complex
Genetic constraint (gnomAD): Loss-of-function variants: 2 observed, 28.93 expected, observed/expected ratio (o/e) 0.0691, 90% interval 0.027 to 0.22. The upper end of that interval is the gene's LOEUF score, 0.22, which puts it in group 1 of 6, group 1 being the genes least tolerant of losing a copy. Missense variants: 114 observed, 299.32 expected, observed/expected ratio (o/e) 0.38, 90% interval 0.33 to 0.44. Synonymous variants: 90 observed, 106.91 expected, observed/expected ratio (o/e) 0.84, 90% interval 0.71 to 1.
Homologues: Orthologues: chimpanzee COPS5 (100% identical), guinea pig COPS5 (100% identical), macaque COPS5 (100% identical), pig COPS5 (100% identical), rabbit COPS5 (100% identical), dog COPS5 (99% identical), mouse Cops5 (99% identical), rat Cops5 (99% identical), tropical clawed frog cops5 (97% identical), zebrafish cops5 (96% identical), Drosophila melanogaster CSN5 (73% identical), Caenorhabditis elegans csn-5 (56% identical). Paralogues in human: PSMD14 (29% identical), BRCC3 (19% identical), EIF3H (16% identical).
Diseases named in the same sentence as COPS5 in open-access papers:
COPS5 is named in the same sentence as 106 diseases in open-access papers, as found by Europe PMC text mining. Sharing a sentence is not in itself a finding about the gene and the disease. The quoted sentences say what the papers report.
breast carcinoma (49 papers, 2008 to 2025). "It is reported that overexpression of Jab1/COPS5 is associated with human epidermal growth factor receptor-2 (HER-2) levels in breast cancer." (PMID 29535627, 2018). "The online data was consistent with the IHC data, suggesting high levels of COPS5 was associated with worse survival in either breast cancer (p=0.00555) or lung cancer (p=0.0439)." (PMID 29228627, 2017). "The online data was consistent with the IHC data, suggesting high levels of either ITGA11 or Jab1/COPS5 was associated with worse survival in breast cancer." (PMID 29383106, 2017). "Jab1/COPS5 expression level associates with EGFR level in breast cancer." (PMID 29535627, 2018). "Furthermore, RNA sequencing analysis of mRNA expression from the GEPIA online database revealed that ITGA11 was associated with Jab1/Cops5 in breast cancer patients." (PMID 29383106, 2017). "Here using integrated genomic and functional studies, we report that amplification and/or overexpression of the COP9 complex-associated isopeptidase COPS5 is presented in about 9% of the ERα+ primary breast cancer and more frequently (86.7%, 26/30) in tamoxifen-resistant tumours." (PMID 27375289, 2016). "Importantly, COPS5 overexpression causes tamoxifen-resistance in preclinical breast cancer models in vitro and in vivo." (PMID 27375289, 2016). "It has been reported that the expression of COPS5 is a prerequisite for the MYC activity in breast cancer." (PMID 38974382, 2024). "COPS5 is required for TNF-α-mediated PD-L1 stabilization in breast cancer cells and inhibition of COPS5 sensitized cancer cells to anti-CTLA4 therapy." (PMID 36304306, 2022). "Most of the current studies focus on the oncogenic function of COPS5, and its dysregulated activity contributes to the development of cancers, such as breast cancer, glioma, and prostate cancer." (PMID 35815279, 2022). "Mechanistically, in breast cancer cells, Lim and colleagues revealed that TNFα induced NF-κB p65 activation, which in turn binds to the COPS5 gene promoter leading to enhanced transcription of CSN5 having de-ubiquitination activity." (PMID 32486375, 2020). "For instance, increased expression levels of OTUD6B, UCH37, VCPIP1, USP7, and COPS5 have been detected in various breast cancers." (PMID 33070427, 2020). "It has been reported that COPS5 plays a crucial role in tamoxifen resistance in oestrogen receptor α (ERα) positive breast cancer patients, through regulating NCoR ubiquitination-proteasomal degradation." (PMID 32703314, 2020). "Our previous studies showed that Jab1/COPS5 was highly expressed in breast cancer and played an essential role in the breast cancer pathogenesis, and that Jab1 knockdown significantly inhibited breast cancer cell proliferation and metastasis." (PMID 31788446, 2019). "Already, many studies have found genes or proteins strongly associated with the progress and prognosis of breast cancer, including enhancer of zeste 2 (EZH2) polycomb repressive complex 2 subunit and Jab1/COPS5." (PMID 31182966, 2019). "It is also confirmed that overexpression of Jab1/COPS5 degrades NCoR protein through the ubiquitination-proteasome pathway in breast cancer." (PMID 29535627, 2018). "Recently, the relevance of COPS5 amplification and overexpression in the tamoxifen-resistance of ERα-positive breast cancer was also reported." (PMID 29755680, 2018). "Through Inhibition of HER-2 by herceptin, Jab1/COPS5 expression was attenuated in various breast cancer cell lines." (PMID 29535627, 2018). "Jab1/COPS5 has been observed to overexpressed in many cancers including colon, ovarian, lung and breast cancer, and so on." (PMID 29535627, 2018). "Abnormal expression of Cops5 was demonstrated to impact carcinogenesis in several cancer types including breast cancer, laryngeal cancer, and oral squamous cell carcinoma (SCC)." (PMID 28587635, 2017).
breast carcinoma (continued). "In the current study, we identified potential genes associated with breast cancer tumorigenesis by transcriptional network analysis and further validated ITGA11 from the STC analysis and a differentially expressed gene Jab1/COPS5 in clinical patients." (PMID 29383106, 2017). "In conclusion, we demonstrated that therapeutic resistant lung cancers and relapse breast cancers are characterized by distinct elevated of Jab1/COPS5." (PMID 29228627, 2017). "The Jab1/COPS5 level was found to be a possible biomarker for clinical response to chemotherapy in lung cancer patients and for postoperative relapse in breast cancer patients who received adjuvant chemotherapy." (PMID 29228627, 2017). "To evaluate the prognostic influence of Jab1/COPS5 expression on breast cancer patients, we performed Kaplan-Meier analyses to compare grouped patients." (PMID 29228627, 2017). "Increased Jab1/COPS5 levels in breast cancer can indicate cancer relapse, although the reason for why the elevated Jab1/COPS5 levels correlates with tumor relapse remains to be elucidated." (PMID 29228627, 2017). "In recent years, a number of studies revealed an association between elevated Jab1/COPS5 level and tumor progression/poor prognosis in several types of cancer, including breast cancer." (PMID 29228627, 2017). "In agreement with the immunohistochemistry results, data from ONCOMINE indicated that ITGA11 and Jab1/Cops5 expression levels tend to be higher in breast cancer with higher grade." (PMID 29383106, 2017). "Relapsed breast cancer patients had an increased Jab1/COPS5 level and breast cancer patients with increased Jab1/COPS5 level had significantly shorter disease-free survival and overall survival." (PMID 29228627, 2017). "In agreement with the immunohistochemistry findings, the data from online database ONCOMINE indicated that ITGA11 and Jab1/Cops5 mRNA expression levels in breast cancer are much higher than those in normal breast tissue." (PMID 29383106, 2017). "The aim of the current study is to examine Jab1/COPS5 expression on both lung and breast cancers and to investigate its role on therapeutic response and cancer relapse." (PMID 29228627, 2017). "The survival curves suggested that patients with high levels of COPS5 had a significant association with worse DFS and OS in breast cancer (OS, p=0.029; DFS, p= 0.044)." (PMID 29228627, 2017). "In this study, data of 88 lung cancer and 76 breast cancer patients were retrospectively collected and analyzed to identify the relationship between the Jab1/COPS5 level and the clinical progression and outcome of these patients." (PMID 29228627, 2017). "To analyze the Jab1/COPS5 expression patterns, we used 88 lung cancer tissue samples (mean age, 59 years; range, 33–81 years) and 76 breast cancer tissue samples (mean age, 49 years; range, 25–80 years)." (PMID 29228627, 2017). "Based on the data we showed in this report, in hormone-sensitive ERα-positive breast cancer normal basal levels of COPS5/COP9 precisely control the protein stability of ERα corepressor NCoR." (PMID 27375289, 2016). "Taken together, it is conceivable that mechanistically overexpression of COPS5 leads to degradation of NCoR protein through the ubiquitination-proteasomal pathway mediated by the COP9 complex in tamoxifen-resistant ERα+ breast cancer cells." (PMID 27375289, 2016). "COPS5 gene is located at the chromosome 8q13 which is amplified (copy number (CN)>6) in about 9% (70/774) of the ERα+ breast cancer (Log2 ESR1 expression>5)." (PMID 27375289, 2016). "It is therefore conceivable that combination of tamoxifen and a COPS5 inhibitor would be a desired therapeutic approach to overcoming tamoxifen-resistance in breast cancer." (PMID 27375289, 2016). "Accumulating evidence suggests critical roles of COPS5 in different stages of breast cancer development." (PMID 27375289, 2016).
breast carcinoma (continued). "We also demonstrate that genetic inhibition of the isopeptidase activity of COPS5 is sufficient to re-sensitize the resistant breast cancer cells to tamoxifen-treatment, offering a potential therapeutic approach for endocrine-resistant breast cancer patients." (PMID 27375289, 2016). "We revealed that NCoR is a substrate of COPS5/COP9 that is crucial in mediating endocrine-resistance in breast cancer." (PMID 27375289, 2016). "Together, these data support that amplification and overexpression of COPS5 in ERα+ breast cancer cells confers resistance to tamoxifen." (PMID 27375289, 2016). "Importantly, expression of a shRNA-resistant WT COPS5 cDNA was able to completely rescue the growth inhibition induced by shRNA, while the isopeptidase-deficient D151N failed to do so, indicating that the catalytic activity of COPS5 is essential to confer tamoxifen-resistance in breast cancer cells." (PMID 27375289, 2016). "We also show evidence that inhibition of the isopeptidase activity of COPS5 is sufficient to re-sensitize the resistant breast cancer cells to tamoxifen-treatment, providing a potential therapeutic approach for endocrine-resistant breast cancer patients." (PMID 27375289, 2016). "It was also proposed that ligand-induced ERα degradation was regulated by COPS5 in hormone-dependent breast cancer cells." (PMID 27375289, 2016). "In summary, the current work supports the idea of developing COPS5 inhibitors to treat tamoxifen-resistant ERα+ breast cancer patients harbouring COPS5 amplification and/or overexpression." (PMID 27375289, 2016). "However, we found support in the literature for the involvement of the selected highly central genes (COPS5, FN1, and CUL3) in breast cancer susceptibility (Sections 3.3, 3.6, and 3.8)." (PMID 33735170, 2021). "COPS5 was found to stabilize PD-L1 in breast cancer through deubiquitination of the PD-L1 molecule." (PMID 34953500, 2021). "Furthermore, COPS5 was found to be involved in breast cancer metastasis as a target gene of miRNA let-7d." (PMID 34993131, 2021). "In this regard, we speculate that COPS5 may regulate VEGFA to promote breast cancer progression, although the mechanism between VEGFA and COPS5 needs to be further explored." (PMID 34993131, 2021). "Not only its overexpression, but also COPS5 gene amplification has been recently reported in ERα-positive breast cancer, supporting that COPS5 might be an oncogene in some cancers." (PMID 29755680, 2018). "Moreover, increased Jab1/COPS5 expression was correlated with worse survival in breast cancer patients." (PMID 29535627, 2018). "NCoR is a molecular target of Jab1/COPS5 which mediates endocrine-resistance in breast cancer." (PMID 29535627, 2018). "Jab1/COPS5 involves in breast cancer progression by regulating a variety of targets." (PMID 29535627, 2018). "Jab1/COPS5 expression was correlated with expression of PD-L1 in breast cancer." (PMID 29535627, 2018). "al., revealed that high levels of Jab1 are significantly enriched in the ERα+ breast cancer patients, implicating that the amplification and overexpression of COPS5 may contribute to the ERα-related signalling and tumour progression." (PMID 29228627, 2017). "As expected, both ITGA11 and Jab1/Cops5 were overexpressed in breast cancer." (PMID 29383106, 2017). "The expression of Jab1/COPS5 in lung cancer or breast cancer was detected by IHC." (PMID 29228627, 2017). "Previous studies reported Jab1/COPS5 overexpressed in breast cancers and therefore Jab1/COPS5 could be an interesting target for breast cancer patients." (PMID 29228627, 2017). "However, COPS5 expression was correlated with ER status (p<0.001) and PR status (p=0.013) in breast cancer patients." (PMID 29228627, 2017). "Accumulating evidence suggests critical roles of Jab1/COPS5 in breast cancer progression." (PMID 29228627, 2017).
breast carcinoma (continued). "High intratumoral levels of Jab1/COPS5 might serve as novel predictive biomarkers to identify chemotherapy resistance in lung cancer or to identify relapse in breast cancer." (PMID 29228627, 2017). "COPS5 is one of the frequently altered genes in ERα+ breast cancer samples from TCGA." (PMID 27375289, 2016). "Finally, we investigated the cancer biological relevance and therapeutic potentials of COPS5-related molecular mechanisms in endocrine-refractory breast cancer." (PMID 27375289, 2016). "It is conceivable that COPS5 might be involved in multiple stages of breast cancer development by regulating different protein targets via its isopeptidase activity." (PMID 27375289, 2016). "Of note, high levels of amplitude (CN>12) of COPS5 are significantly enriched in the ERα+ breast cancer patients, implicating that the amplification and overexpression of COPS5 may contribute to the ERα-related signalling and tumour progression." (PMID 27375289, 2016). "In addition, COPS5 has been shown to be involved in breast cancer initiation by coordinating the epithelial transformation evoked by Myc and Ras in mouse models." (PMID 27375289, 2016). "Of note, breast cancer cells with overexpression of COPS5 appeared to be less sensitive to the SERD fulvestrant in vitro as well, suggesting that it could be a common resistance mechanism to endocrine therapies." (PMID 27375289, 2016). "In addition, the clinical outcomes (disease-free survival rate and overall survival rate) of the TCGA breast cancer patients (including luminal A and B) with high expression levels of COPS5 appeared to be poorer." (PMID 27375289, 2016). "However, the role of Jab1/COPS5 on breast cancer relapse needs to be elucidated." (PMID 29228627, 2017). "Interestingly, overexpression of COPS5 induces ubiquitination and proteasomal degradation of the NCoR protein, a key corepressor of tamoxifen-bound ERα, leading to de-repression of ERα target genes in resistant breast cancer." (PMID 27375289, 2016). "In breast cancer, TNF-α induces activation of p65, which binds to the COPS5 gene promoter leading to enhanced transcription of CSN5 and de-ubiquitination activity." (PMID 36531159, 2022). "Jab1/COPS5 is highly expressed in various tumors, including nasopharyngeal carcinoma, non-small-cell lung cancer, liver cancer, colon cancer, and breast cancer." (PMID 31788446, 2019). "Data downloaded from cBioportal shows that 41.4, 22.9, and 20.7% genetic alterations of Jab1/COPS5 have been recorded in neuroendocrine prostate cancer (NEPC), colorectal adenocarcinoma triplets (MSKCC) and breast cancer, respectively." (PMID 29535627, 2018). "Multivariate analysis identified COPS5 high expression as significant independent factor for poor DSF and OS in breast cancer." (PMID 29228627, 2017). "We also investigated the relationship between ITGA11 and Jab1/COPS5 and survival of breast cancer patients in GEPIA database." (PMID 29383106, 2017). "In conclusion, this study identified Jab1/COPS5 as novel prognostic markers for lung cancer and breast cancer." (PMID 29228627, 2017). "Histological type (p=0.017 for DSF; p=0.049 for OS) and COPS5 (p=0.001 for DSF; p=0.050 for OS) were significant prognostic factors for breast cancer." (PMID 29228627, 2017). "This study aims to further evaluate the clinical and prognostic value of Jab1/COPS5 level as a biomarker in lung and breast cancer patients receiving adjuvant chemotherapy." (PMID 29228627, 2017). "Studies on Jab1/COPS5 has focused on identification of tumor types that show Jab1/COPS5 overexpression, including colon, ovarian, lung and breast cancer." (PMID 29228627, 2017). "Amplification and overexpression of COPS5, a catalytic subunit of the COP9 complex, is present in about 9% of the ERα+ primary breast cancer and more frequently (86.7%, 26/30) in tamoxifen-refractory tumours." (PMID 27375289, 2016).